MOCS3 (molybdenum cofactor synthesis 3)
Description:
Plays a central role in 2-thiolation of mcm(5)S(2)U at tRNA wobble positions of cytosolic tRNA(Lys), tRNA(Glu) and tRNA(Gln). Also essential during biosynthesis of the molybdenum cofactor. Acts by mediating the C-terminal thiocarboxylation of sulfur carriers URM1 and MOCS2A. Its N-terminus first activates URM1 and MOCS2A as acyl-adenylates (-COAMP), then the persulfide sulfur on the catalytic cysteine is transferred to URM1 and MOCS2A to form thiocarboxylation (-COSH) of their C-terminus. The reaction probably involves hydrogen sulfide that is generated from the persulfide intermediate and that acts as a nucleophile towards URM1 and MOCS2A. Subsequently, a transient disulfide bond is formed. Does not use thiosulfate as sulfur donor; NFS1 acting as a sulfur donor for thiocarboxylation reactions.
Synonyms: UBA4; dJ914P20.3; MOCODB2
Tractability: PROTAC: ubiquitination databases record sites on it; its protein half-life has been measured.
Target class: Enzyme; Transferase
Gene: Protein-coding gene on chromosome 20 (50,958,818 to 50,963,929, forward strand). Ensembl gene ENSG00000124217.
Subcellular location: Cytoplasm, cytosol
Pathways (Reactome):
Metabolism: Molybdenum cofactor biosynthesis
Gene Ontology:
Molecular function: molybdopterin-synthase adenylyltransferase activity; molybdopterin-synthase sulfurtransferase activity; nucleotidyltransferase activity; protein binding; sulfurtransferase activity; URM1 activating enzyme activity; thiosulfate-cyanide sulfurtransferase activity; adenylyltransferase activity; ubiquitin-like modifier activating enzyme activity
Biological process: Mo-molybdopterin cofactor biosynthetic process; tRNA thio-modification; tRNA wobble uridine modification; protein urmylation; tRNA wobble position uridine thiolation
Cellular component: cytosol; cytoplasm
Genetic constraint (gnomAD): Loss-of-function variants: 9 observed, 8.92 expected, observed/expected ratio (o/e) 1.01, 90% interval 0.61 to 1.7. That is too few expected variants to judge how well the gene tolerates losing a copy. Missense variants: 581 observed, 625.47 expected, observed/expected ratio (o/e) 0.93, 90% interval 0.87 to 1. Synonymous variants: 294 observed, 283.25 expected, observed/expected ratio (o/e) 1.04, 90% interval 0.94 to 1.14.
Homologues: Orthologues: chimpanzee MOCS3 (99% identical), macaque MOCS3 (95% identical), dog MOCS3 (92% identical), pig MOCS3 (90% identical), guinea pig MOCS3 (90% identical), rabbit MOCS3 (84% identical), rat Mocs3 (80% identical), mouse Mocs3 (80% identical), zebrafish mocs3 (60% identical), tropical clawed frog mocs3 (57% identical), Drosophila melanogaster Uba4 (48% identical), Caenorhabditis elegans moc-3 (40% identical). Paralogues in human: UBA5 (22% identical), UBA7 (22% identical), UBA1 (21% identical), UBA6 (20% identical), ATG7 (20% identical), UBA2 (16% identical), UBA3 (13% identical), NAE1 (7% identical), SAE1 (6% identical).
Diseases named in the same sentence as MOCS3 in open-access papers:
MOCS3 is named in the same sentence as 3 diseases in open-access papers, as found by Europe PMC text mining. Sharing a sentence is not in itself a finding about the gene and the disease. The quoted sentences say what the papers report.
Molybdenum Cofactor Deficiency (3 papers, 2021 to 2025). "Xanthinuria type III is caused by molybdenum cofactor deficiency (MoCD) due to pathogenic variants in MOCS1, MOCS2, MOCS3, or GEPH genes." (PMID 40707723, 2025). "Molybdenum cofactor deficiency (MoCD) is a rare and severe autosomal recessive in-born error of metabolism caused by the mutation in MOCS1, MOCS2, MOCS3 or GEPH genes, with an incidence ranging between 1 in 100,000 and 200,000 live births." (PMID 37371303, 2023).
MOCS3 also shares sentences with these, for which no sentence is quoted: Encephalopathy (1 paper); microcephaly (1).